IL23R (interleukin 23 receptor)
Diseases named in the same sentence as IL23R in open-access papers (continued):
Sharing a sentence is not in itself a finding about the gene and the disease.
periodontitis (6 papers, 2020 to 2026). An acute or chronic inflammatory process that affects the tissues that surround and support the teeth. "The objective of this systematic review was to identify genetic variants of the IL‐23, IL‐17, IL‐23R and IL‐17R genes and isoforms and its possible association with increased development of periodontitis and peri‐implantitis." (PMID 39887950, 2025). "Another study indicates a reverse relationship between IL-23R and IL-17RA in chronic and aggressive periodontitis patients, potentially linked to RANKL activation and alveolar bone loss." (PMID 39659491, 2024). "IL‐23 is known to cause IL‐23R overexpression in several cell types; thus, IL‐23 upregulation in periodontitis could cause IL‐23R overexpression in this pathology." (PMID 41536464, 2026). "Finally, concerning the IL‐23R gene, two studies evaluated the missense variant rs 11209026 in 277 individuals with periodontitis." (PMID 39887950, 2025). "Meanwhile, in the group of patients with periodontitis, significant correlations were found between: IL‐23R and IL‐23 [r = 0.469 (p = 0.021)]; as well as between IL‐17RA and IL‐17A [r = 0.713(p < 0.001)] and with IL‐23 [r = 0.637 (p = 0.001)]." (PMID 41536464, 2026). "There is a tendency toward increased IL‐23, IL‐17, and IL‐17 receptor (IL‐17RA) and a discrepancy in IL‐23 receptor (IL‐23R) in gingival tissue (GT) of patients with periodontitis." (PMID 41536464, 2026). "Although western blotting (WB) is a semi‐quantitative technique, it can reveal protein expression trends and elucidate the discrepancy of IL‐23R in GT in periodontitis." (PMID 41536464, 2026). "We found a significant increase in IL‐23, IL‐17A, IL‐23R, and IL‐17RA protein levels in the periodontitis group compared with the healthy group; we also detected bands with unexpected molecular weights for both receptors." (PMID 41536464, 2026). "We previously reported a decrease in IL‐23R in GT of subjects with periodontitis compared with healthy subjects based on a sandwich ELISA." (PMID 41536464, 2026). "At protein level, we demonstrated an increase in IL‐17RA and, conversely, a decrease in IL‐23R in GT from patients with periodontitis compared to healthy subjects using the ELISA technique." (PMID 41536464, 2026). "In this study, IL‐23R expression was analyzed, and a significant increase was observed in the periodontitis group compared with the control group." (PMID 41536464, 2026). "IL‐23R (72 kDa) expression was significantly higher in the periodontitis group (median 0.491, IQR 1.137) compared with healthy subjects (median 0.272, IQR 0.180; p = 0.006)." (PMID 41536464, 2026). "Comparing Oral Leukoplakia and Oral Lichen with Periodontitis, both potentially malignant transforming lesions showed significantly (p=0.029) increased IL-23R cell densities and Labeling Indices as well as a significantly increased CD163/CD11c ratio (p=0.029)." (PMID 40297579, 2025). "On T-cells, IL-23R signaling leads to the induction of a Th17 phenotype which is believed to contribute to the pathogenesis of periodontitis In contrast, the role of IL-23R activation on other immune cells is poorly understood." (PMID 40297579, 2025). "This study analyzed six genetic variations of IL‐17A, IL‐17F, IL‐17R, and IL‐23R genes in people with periodontitis and peri‐implantitis." (PMID 39887950, 2025). "Semi‐quantitatively, using WB, we found overexpression of the IL‐23/IL‐17A axis and its receptors in the GT of patients with periodontitis, which coincides with several authors, including the expression of IL‐23R, which we had previously found to be decreased by the ELISA method." (PMID 41536464, 2026). "An analysis of N‐glycan removal, LC/MS/MS, and peptide mapping could help elucidate whether these bands are immature proteins or isoforms of IL‐23R and IL‐17RA in periodontitis." (PMID 41536464, 2026). "These advantages may be why IL‐23R (72 kDa) was increased in GT of patients with periodontitis in this study." (PMID 41536464, 2026).
periodontitis (continued). "This study analyzed a total of twenty‐eight genetic variants corresponding to the IL‐17A: rs 2275913 (68.4%), rs 3819024 (5.3%), rs 10484879 (5.3%); IL‐17F: rs 763780 (47.4%), IL‐17R: rs 879576 (11%) and IL‐23R: rs 11209026 (11%) genes in subjects with periodontitis and peri‐implantitis." (PMID 39887950, 2025). "Regarding IL‐23R, two articles in this review evaluated the polymorphism (rs11209026) for which they did not observe an association with the risk or aggravation of periodontitis." (PMID 39887950, 2025). "Another sensitive and specific technique that could be used to quantitatively measure IL‐23/IL‐17 axis molecules in the GT of patients with periodontitis, in addition to clarifying the behavior of IL‐23R is liquid chromatography‐tandem mass spectrometry (LC/MS/MS)." (PMID 41536464, 2026). "Another way in which IL‐23R isoforms can be formed is by transmembrane cleavage by a disintegrin and metalloprotease 10 and 17 (ADAM10 and ADAM17), of which ADAM17 has been found to be elevated in patients with periodontitis." (PMID 41536464, 2026). "The current analysis did not reveal significant differences in IL-23R and macrophage marker expression between healthy Controls and Periodontitis (PD) samples." (PMID 40297579, 2025).
Vogt-Koyanagi-Harada disease (6 papers, 2013 to 2025). A bilateral, chronic, diffuse granulomatous panuveitis typically characterized by serous retinal detachment and frequently associated with neurological (meningitis), auditory, and dermatological alterations. "rs78377598 and rs1176338 in IL23R-C1orf141 had an increased risk of VKH disease in all ethnic populations." (PMID 32437414, 2020). "In the current study, we confirmed the significant association of rs78377598 and rs117633859 in IL23R-C1orf141 with VKH disease in the Japanese popualtion." (PMID 32437414, 2020). "Taken together, IL23R are likely involved in the development of VKH disease through genetic variants of IL23R-C1orf141." (PMID 32437414, 2020). "In conclusion, the current study confirmed a significant association between VKH disease and the two loci, IL23R-C1orf141 and ADO-ZNF365-EGR2, in the Japanese population, suggesting that genetic variants in these loci play important roles in disease development." (PMID 32437414, 2020). "The disease-risk allele frequencies of IL23R-C1orf141 are lower in Caucasians (2.5% in Caucasians from 1000 Genomes Project Phase 3) that have a low prevalence of VKH disease than in Asians, and those of ADO-ZNF365-EGR2 in Caucasians (52.0%) are higher in Asians." (PMID 32437414, 2020). "In these studies, IL23R-C1orf141 on 1q31.2 was associated with VKH disease among patients of Han Chinese descent in Singapore but not in those of other Asian ethnicities." (PMID 32437414, 2020). "Thus, the IL23R-C1orf141 and ADO-ZNF365-EGR2 loci may play important roles in the development of VKH disease through genetic polymorphisms." (PMID 32437414, 2020).
asthma (5 papers, 2019 to 2022). "It has been found that IL-17A is associated with severe asthma and requires IL-23 receptor (IL-23R) signalling, which is adversely controlled by let-7f microRNA." (PMID 36362795, 2022). "In a HDM mouse model, the expression of IL-23R by T cells, macrophages, and DCs was evaluated to underline the impact of IL-23-IL-23R signaling as a potential target in neutrophilic allergic airway inflammation for a novel asthma therapy." (PMID 35475923, 2022). "There are variants of the IL-23R gene, which are protective or, conversely, predisposing for asthma and other groups of IL-23R-related chronic inflammatory diseases." (PMID 35475923, 2022). "IL-17A is associated with severe asthma and requires IL-23R signaling, which is negatively regulated by let-7f miRNA in CD4+ lymphocytes." (PMID 31071965, 2019). "Compared to men, TH17 cells of both women with severe asthma and healthy controls produced more IL-17A, increased the expression of IL-23R, while decreased let-7f microRNA expression." (PMID 36362795, 2022). "By contrast, treatment with inactivated M. phlei caused symptom alleviation and near normalization otherwise increased percentages of Th-17-like γδ T and IL-23R+ γδ T in murine model of asthma." (PMID 33661375, 2021). "Let-7f expression was lower and IL-23R expression was higher in TH17-differentiated cells from women compared with men with severe asthma." (PMID 31071965, 2019). "Moreover, an increase in IL-23R+ γδ T cells was observed in BALF in murine model of asthma." (PMID 33661375, 2021).
atherosclerosis (5 papers, 2020 to 2023). A disease characterized by the build-up of fatty material and calcium deposition in the arterial wall resulting in partial or complete occlusion of the arterial lumen. "The functional single-nucleotide polymorphism (SNP) rs11209026 G/A in IL-23R, which is associated with reduced IL-23 receptor signal transmission, is described to be protective against atherosclerosis progression." (PMID 36012327, 2022). "Enforced IL-22 signaling by administration of recombinant protein rectified IL-23/IL-23R deficiency and ameliorated atherosclerosis." (PMID 33562334, 2021). "However, genetic ablation of IL-23 or IL-23R in hematopoietic cells unexpectedly accelerates atherosclerosis development, particularly due to the loss of downstream IL-22 expression and IL-22-dependent intestinal homeostasis and host–microbiota détente." (PMID 33562334, 2021). "Moreover, IL-23R deficiency in hematopoietic cells resulted in significantly increased atherosclerosis progression." (PMID 33227973, 2020).
enthesitis (5 papers, 2011 to 2024). Inflammation at the site of insertion of ligaments, tendons, and other fibrous structures into bone. "IL-23 overexpression in mice causes a florid enthesitis which is driven by enthesis resident population of IL-23R positive innate T-cells that drove IL-17A dependent pathology." (PMID 30505307, 2018). "The question of how these genotypes might result in a particular clinical phenotype is unclear, but the work of Sherlock and colleagues would suggest that in a mouse model the development of enthesitis may be linked to the presence of a particular subset of T cells (IL-23R+, CD3+CD4−CD8−)." (PMID 25948071, 2015). "The normal human spinal entheses harbor type 3 ILCs IL-23R expressing cells, capable of IL-17 production, and are therefore also potential mediators of IL-23 driven enthesitis." (PMID 30505307, 2018).
lung carcinoma (5 papers, 2013 to 2021). "We showed previously that spliced variants of IL-23R could generate defective IL-23R in various human tumor cell lines and different lung cancer tissues that might be a possible mechanism to account for the escape of immune surveillance in some human cancers." (PMID 24351840, 2013). "Recent study shows that IL-23 regulates the proliferation versus inhibition of IL-23R positive lung cancer cells in a concentration dependent manner." (PMID 24351840, 2013). "Notably, investigators have previously demonstrated that low concentrations of IL-23 bind to IL-23R and promote lung cancer cell growth, whereas high concentrations of IL-23 binds to both IL-23R and IL-12β1 to inhibit lung cancer growth." (PMID 34093846, 2021). "In IL-23R knockout mice, the tumor growth of both B16F10 melanoma and LL2 lung carcinoma were inhibited in the IL-23R−/− mice." (PMID 23802098, 2013).
psoriasis vulgaris (5 papers, 2010 to 2024). Plaque psoriasis is the most common presentation of psoriasis. "Pre-selected SNP sets were associated with psoriasis vulgaris analysis, which was used to identify four SNP-associated targeted therapy efficiencies: IL1β (rs1143633), IL4 (IL13) (rs20541), IL23R (rs2201841), and TNFα (rs1800629) genes." (PMID 33383665, 2020).
chronic mucocutaneous candidiasis (4 papers, 2021 to 2025). "However, the susceptibility of certain individuals with deficiencies in IL-12B, IL-12Rβ1, or IL-23R to chronic mucocutaneous candidiasis (CMC) indicates the crucial role of human IL-23 in defending against mucocutaneous Candida spp." (PMID 38535546, 2024).
diabetes (4 papers, 2011 to 2024). "A detailed genotype-phenotype analysis of IL-23R rs10889677 was conducted among gout patients in relation to clinical factors including demographic characteristics and serum biochemical parameters, as well as tophi and previous medical history (hypertension, diabetes mellitus, and obesity)." (PMID 26399911, 2015).
esophageal cancer (4 papers, 2012 to 2024). A primary or metastatic malignant neoplasm involving the esophagus. "The IL-23R rs6682925 T>C and rs1884444 T>G variant genotypes were found to be significantly associated with an elevated risk of esophageal cancer in comparison to the corresponding wild-type homozygotes." (PMID 39796684, 2024). "Although the exact mechanisms by which IL23R modulates cancer susceptibility are still unclear, the key role of IL23R in cancer has been demonstrated by recent genetic studies in which genetic variants in the IL23R gene were associated with oral, gastric and esophageal cancer." (PMID 23239971, 2012). "The role of the IL-23R gene in the etiology of esophageal cancer remains a topic of debate in the scientific community." (PMID 39796684, 2024). "Stratification analysis of the IL-23R rs10889677A>C genotypes by selected variables in esophageal cancer patients and controls." (PMID 24586528, 2014).
gout (4 papers, 2015 to 2024). A condition characterized by painful swelling of the joints, which is caused by deposition of urate crystals. "Rs7517847 and rs10889677 of the IL-23R gene were associated with gout in studies of Chinese Han male cohorts." (PMID 30123371, 2018). "In our previous work, we identified associations between gout and SNPs in IL-17-related genes IL-23R rs7517847 and IL-8 −251T/A." (PMID 26890073, 2016). "We found that IL-23R rs10889677 was significantly associated with susceptibility to gout in Chinese Han male individuals." (PMID 26399911, 2015). "These include geranylgeranyl transferase I beta subunit (PGGT1B), histone H3 protein (H3K4me1), IL-1β, interleukin-23 receptor (IL-23R), all of which may increase the risk of gout occurrence." (PMID 39432655, 2024). "Our results revealed that the rs10889677 variant in IL-23R may be involved in the development of gout in Chinese Han male individuals." (PMID 26399911, 2015). "Sites rs10889677 and rs7517847 of IL-23R were independent to each other and this may demonstrated IL-23R as an important candidate gene for gout susceptibility." (PMID 26399911, 2015). "However, despite these limitations, our study demonstrated an association between IL-23R and susceptibility to gout in Chinese Han male individuals." (PMID 26399911, 2015). "We detected a significant difference in genotype frequency of IL-23R rs10889677 (χ2 = 81.39, P < 0.001) between gout patients and controls." (PMID 26399911, 2015). "We therefore propose IL-33, IL-1RL1, IL-23R, and STAT4 as potential candidate susceptibility genes for gout." (PMID 26399911, 2015). "The current study therefore aimed to investigate the associations between the IL-33 rs3939286 A/G, IL-1RL1 rs13015714 G/T, IL-23R rs10889677 A/C, and STAT4 rs7574865 G/T single nucleotide polymorphisms (SNPs) and the risk of gout." (PMID 26399911, 2015). "There was a significant difference in genotypic frequencies of IL-23R rs10889677 between gout patients and controls (χ2 = 81.386, P < 0.001)." (PMID 26399911, 2015). "The aim of this study was to investigate the associations between genetic variants in the interleukin (IL) and interleukin receptor (ILR) genes IL-33, IL-1RL1, IL-23R, and signal transducer and activator of transcription 4 (STAT4) and susceptibility to gout in Chinese Han male individuals." (PMID 26399911, 2015). "The production and function of cytokines may be affected by polymorphisms in the functional regions of their genes, suggesting that IL-33, IL-1RL1, IL-23R, and STAT4 may be candidate genes for the inflammatory pathogenesis of gout." (PMID 26399911, 2015). "The genetic distributions of rs3939286 in IL-33, rs13015714 in IL-1RL1, rs10889677 in IL-23R, and rs7574865 in STAT4 were detected in 1100 men with gout and 1227 ethnically matched controls, using Taqman allelic discrimination real-time polymerase chain reaction (PCR)." (PMID 26399911, 2015).
hepatocellular carcinoma (4 papers, 2017 to 2025). A malignant tumor that arises from hepatocytes. "The wild-type IL-23R GG genotype has been identified as an important risk factor for the development of hepatocellular carcinoma." (PMID 39796684, 2024). "It has been hypothesized that variants of the IL-23R gene are involved in the etiology of hepatocellular carcinoma in patients with hepatitis C virus (HCV) infection." (PMID 39796684, 2024). "The IL-23R rs1884444T/G polymorphism has been reported to be associated with various diseases, including cavitary lesion of pulmonary tuberculosis in Chinese Uygurs, Alzheimer’s disease in Han Chinese, and increased risk of hepatocellular carcinoma." (PMID 29050281, 2017). "A correlation was observed between IL-23R rs17375018 and genetic susceptibility to hepatocellular carcinoma (HCC)." (PMID 39796684, 2024). "Immunofluorescence staining confirmed positive expression of IL-23R on these 3 hepatoma cell lines." (PMID 29983862, 2018). "Expression of the IL-23R in liver cancer cells inferred that hepatoma cells might be the potential targets of IL-23." (PMID 29983862, 2018). "Three single-nucleotide polymorphisms in the IL-23R gene (rs10889677, rs1884444, and rs11465817) were investigated in a cohort of 84 patients with chronic hepatitis B, 67 patients with HBV-related liver cirrhosis, 89 patients with HBV-related hepatocellular carcinoma, and 94 healthy controls." (PMID 39796684, 2024). "Inflammation in hepatocellular carcinoma (HCC) is a key factor in treatment resistance and understanding IL-23R's impact could provide insights into patient variability in drug response, potentially improving Sorafenib efficacy and enhancing treatment outcomes." (PMID 39921803, 2025).
lupus nephritis (4 papers, 2010 to 2022). Glomerulonephritis in the context of systemic lupus erythematosus. "Indeed, lower numbers of IL-17A-producing Th17 cells in IL-23R-deficient B6/lpr mice resulted in reduced anti-DNA antibody levels and lupus nephritis." (PMID 36248812, 2022).